BAX (BCL2 associated X, apoptosis regulator)
Description:
Plays a role in the mitochondrial apoptotic process. Under normal conditions, BAX is largely cytosolic via constant retrotranslocation from mitochondria to the cytosol mediated by BCL2L1/Bcl-xL, which avoids accumulation of toxic BAX levels at the mitochondrial outer membrane (MOM). Under stress conditions, undergoes a conformation change that causes translocation to the mitochondrion membrane, leading to the release of cytochrome c that then triggers apoptosis. Promotes activation of CASP3, and thereby apoptosis.
Synonyms: BCL2L4
Tractability: Small molecule: a structure with a bound ligand is known; a high-quality ligand is known. Antibody: UniProt predicts a signal peptide or a membrane-spanning region. PROTAC: UniProt records ubiquitination sites on it; ubiquitination databases record sites on it; its protein half-life has been measured; a small molecule that binds it is known.
Target class: Ion channel; Other ion channel; Bcl-2 family; Miscellaneous ion channel
Gene: Protein-coding gene on chromosome 19 (48,954,815 to 48,961,798, forward strand). Ensembl gene ENSG00000087088.
Subcellular location: Mitochondrion outer membrane (Isoform Alpha); Cytoplasm; Nucleus; Cytoplasm (Isoform Beta); Cytoplasm (Isoform Gamma); Cytoplasm (Isoform Delta)
Subcellular location (Human Protein Atlas): Vesicles; Plasma membrane
Pathways (Reactome):
Gene expression (Transcription): Transcriptional regulation by RUNX2
Programmed Cell Death: Activation, translocation and oligomerization of BAX; Pyroptosis; Release of apoptotic factors from the mitochondria
Signal Transduction: NTRK3 as a dependence receptor
Gene Ontology:
Molecular function: BH3 domain binding; channel activity; identical protein binding; lipid binding; protein binding; protein heterodimerization activity; protein homodimerization activity; Hsp70 protein binding; protein-folding chaperone binding
Biological process: apoptotic mitochondrial changes; apoptotic process; apoptotic signaling pathway; B cell apoptotic process; B cell receptor apoptotic signaling pathway; cellular response to virus; establishment or maintenance of transmembrane electrochemical gradient; execution phase of apoptosis; extrinsic apoptotic signaling pathway; intrinsic apoptotic signaling pathway; intrinsic apoptotic signaling pathway in response to DNA damage; mitochondrial fragmentation involved in apoptotic process; mitochondrial fusion; negative regulation of mitochondrial membrane potential; negative regulation of protein binding; positive regulation of apoptotic DNA fragmentation; positive regulation of apoptotic process; positive regulation of intrinsic apoptotic signaling pathway; positive regulation of neuron apoptotic process; positive regulation of protein-containing complex assembly; positive regulation of release of cytochrome c from mitochondria; regulation of apoptotic process; regulation of mitochondrial membrane potential; release of cytochrome c from mitochondria; release of matrix enzymes from mitochondria; and 13 more
Cellular component: BAK complex; BAX complex; Bcl-2 family protein complex; cell periphery; cytoplasm; cytosol; endoplasmic reticulum; endoplasmic reticulum membrane; extracellular exosome; membrane; mitochondrial outer membrane; mitochondrial permeability transition pore complex; mitochondrion; nuclear envelope; nucleus; pore complex; mitochondrial membrane
Genetic constraint (gnomAD): Loss-of-function variants: 21 observed, 24.28 expected, observed/expected ratio (o/e) 0.86, 90% interval 0.61 to 1.25. The upper end of that interval is the gene's LOEUF score, 1.25, which puts it in group 5 of 6, group 1 being the genes least tolerant of losing a copy. Missense variants: 236 observed, 246.63 expected, observed/expected ratio (o/e) 0.96, 90% interval 0.86 to 1.07. Synonymous variants: 110 observed, 99.21 expected, observed/expected ratio (o/e) 1.11, 90% interval 0.95 to 1.3.
Cancer hallmarks: proliferative signalling (promotes); escaping programmed cell death (suppresses); genome instability and mutations; change of cellular energetics; suppression of growth (promotes); invasion and metastasis (suppresses); invasion and metastasis (promotes)
Homologues: Orthologues: dog BAX (97% identical), pig BAX (96% identical), rabbit BAX (93% identical), guinea pig BAX (92% identical), mouse Bax (92% identical), rat Bax (91% identical), macaque BAX (73% identical), chimpanzee BAX (64% identical), tropical clawed frog bax (60% identical), zebrafish baxa (49% identical), zebrafish baxb (25% identical), Caenorhabditis elegans ced-9 (18% identical). Paralogues in human: MCL1 (24% identical), BCL2 (23% identical), BCL2L1 (22% identical), BAK1 (21% identical), BOK (21% identical), BCL2A1 (20% identical), BCL2L10 (20% identical), BCL2L2 (19% identical).
Diseases named in the same sentence as BAX in open-access papers:
BAX is named in the same sentence as 367 diseases in open-access papers, as found by Europe PMC text mining. Sharing a sentence is not in itself a finding about the gene and the disease. The quoted sentences say what the papers report.
breast cancer (169 papers, 2003 to 2026). A primary or metastatic malignant neoplasm involving the breast. "ESR1, BRCA1, CTNNB1, and BAX was associated with breast cancer cells proliferation, we further employed Ki67 immunohistochemical staining to evaluate tumor cell proliferation." (PMID 39045563, 2024). "Focusing on the role of BAX and Bcl-2, these proteins are intricately linked to apoptosis and their expression carries prognostic implications in breast cancer." (PMID 38256428, 2024). "In the analysis of BAX G(-248) A gene polymorphism, homozygote expression (AA genotype) of BAX-248A allele was associated with 5 times increased risk of breast cancer (OR = 5.43, 95% CI = 1.70–15.84; P = 0.002)." (PMID 35320970, 2022). "In our study, women with homozygote BAX-248A allele (AA genotype) had 5 times more risk of developing breast cancer." (PMID 35320970, 2022). "Quercetin decreases the viability and proliferation of MCF-7 breast cancer cells through apoptosis activation, via increasing the levels of Bcl-2-associated X protein (BAX) and caspase-3 expression and decreasing Bcl-2 expression." (PMID 32102219, 2020). "EGCG applied to MD-MB-231 human breast cancer cells led to reduced cell growth and apoptosis related to stimulation of Bcl-2-associated X protein (BAX), cleavage of poly (ADP-ribose) polymerase protein (PARP) and reduction of Bcl-2 expression." (PMID 29558948, 2018). "The pro-apoptotic acting protein BAX was induced by both CpG-ODN and LPS in MDA-MB-435-Hyg breast cancer cells, whereas only LPS stimulation caused increased BAX levels in M13SV1-EGFP-Neo breast epithelial cells." (PMID 27187369, 2016). "To determine the mechanism underlying 5-FU-induced alteration of BAX and Bcl-2 genes, we conducted RT-PCR analysis of breast cancer cells after serial diluted 5-FU treatment (0.5, 1.0, and 5.0 μg/ml), and total RNA was extracted at 3, 6, 9, and 24 h." (PMID 26716512, 2016). "Their expression is often disturbed in malignant tissue, and reduced expression of BAD and BAX is associated with poor prognosis in breast cancer." (PMID 21542898, 2011). "In patients with breast cancer, loss of BAX immunostaining was associated with a decreased response to chemotherapy and shorter survival." (PMID 12592374, 2003). "In addition to frameshift mutations caused by dMMR, mutations in the promoter region of the BAX gene have been reported to contribute to reduced BAX expression in chronic lymphocytic leukemia, head and neck squamous cell carcinoma, and breast cancer." (PMID 40869124, 2025). "For example, BAX gene frame-shift mutations can contribute to colon, lung, and T-cell acute lymphocytic leukemia cancer progression and the loss of BAX expression can give rise to accelerated mammary tumor development in mice models." (PMID 33925117, 2021). "In conclusion, we could show a significantly enhanced breast cancer risk associated with the Pro-allele, a significantly later age at breast cancer onset for Pro/Pro patients, and significantly lower p21 and BAX mRNA levels in the tumors of Pro-allele carriers." (PMID 23071787, 2012). "Numerous studies have also revealed that proteins related to the apoptotic pathway, such as BAX, Bcl-2 and Caspase-3, play significant roles in the occurrence of malignant tumors such as esophageal cancer, breast cancer, pancreatic cancer and prostate cancer." (PMID 41411247, 2025).
breast cancer (continued). "Beta-sitosterol treatment induces G1 phase cell cycle arrest in MDA-MB-231 breast cancer cells by downregulating cyclin D1 and upregulating pro-apoptotic proteins like BAX." (PMID 40143209, 2025). "In brain metastases of breast cancer, BAX protein expression was significantly higher than in primary tumors, despite reduced mRNA levels." (PMID 40940401, 2025). "Ginestin has shown effects on Akt, NF-κB, matrix metalloproteinases (MMPs), and BAX/Bcl-2 signaling pathways for breast cancer prevention in C57Bl/6 mice." (PMID 39246660, 2024). "A specific study examining the expression of Bcl-2 and BAX as prognostic markers in breast cancer found that Bcl-2 expression correlated with a better prognosis across all molecular subtypes, including Luminal A breast cancer." (PMID 38256428, 2024). "Serological markers are of significant importance in both the diagnosis and prognosis of breast cancer, with Ki67, CA 15-3, BAX, and Bcl-2 being notably characteristic in luminal subtype tumors." (PMID 38256428, 2024). "For example, in breast cancer, patients with BAX alteration showed poor prognosis in OS (Overall survival), DSS (Disease-specific survival) and PFS (Progress free survival) (p < 0.05)." (PMID 39074253, 2024). "BAX inhibition can promote the growth of breast cancer, and progesterone induces the apoptosis of ovarian and endometrial cancer cells by activating caspase-8, calcitriol, and the caspase-9 pathway." (PMID 37263638, 2023). "BAX has been extensively studied in many types of cancer, including pancreatic cancer, colon cancer, ovarian cancer, lung cancer and breast cancer." (PMID 38003498, 2023). "Compared to MENs+DOX without MF, MENs+DOX with 45 min MF significantly decreased the expression level of BCL2 and enhanced the expression level of BAX and Caspase 3 genes in 4T1 breast cancer cells." (PMID 37845238, 2023). "A cell viability assay, a flow cytometer analysis of apoptosis and cell cycle phases, and protein activity of BAX and Bcl-2 were performed on two human breast cancer cell lines—MCF-7 and MCF-7/DOX." (PMID 36672406, 2023). "Recent studies have reported that Ferula assa-foetida L. essential oil nano-emulsion can lead to apoptosis by decreasing BCL-2 and increasing BAX expression in MCF7 breast cancer cells." (PMID 38138502, 2023). "Previous studies show that all X-chromosome-located RBMX genes are significantly up-regulated in breast cancer and correlate positively with the expression of the pro-apoptotic gene, BAX." (PMID 37805597, 2023). "Similar results were also observed in the study on MCF-7 breast cancer cell line that the regulation of VD3 on apoptosis was BAX and BCL2 depended." (PMID 36159807, 2022). "STAT3 is a transcription factor for breast cancer proliferation-associated genes such as CCND1, c-myc, BCL2, and BAX." (PMID 36106139, 2022). "Increased caspase 3 and 8, along with BAX expression and decreased PARP and BCL-XL gene expression, were implicated in apoptosis induction in breast cancer cells." (PMID 36676955, 2022).
breast cancer (continued). "The treatment of drug-resistant MDA-MB-231 breast cancer cells with tangeretin induced apoptosis by increasing BAX, caspase-3, and -8 and decreasing Bcl-2." (PMID 36142874, 2022). "This study is aimed at determining the association of XRCC3 Thr241Met (rs861539), XRCC4 G(-1394) T (rs6869366) DNA repair and BAX G(-248) A (rs4645878), and BCL2 C(-938) A (rs2279115) apoptotic gene polymorphisms with breast cancer." (PMID 35320970, 2022). "The previous reports on the phytochemical-mediated increase in caspase-3/8 and BAX and the decrease in the Bcl2-level-induced apoptosis in breast cancer cells corroborates our findings." (PMID 36676955, 2022). "In our study, we investigated the relationship between breast cancer risk and genetic variations in DNA repair [XRCC3 Thr241Met and XRCC4 G(‐1394) T] and apoptosis [BAX G(-248) A and BCL-2 C(‐938) A] pathways." (PMID 35320970, 2022). "An experiment conducted by Lei Hu proved that breast cancer cells were stimulated to undergo pyroptosis via BAK or BAX/caspase-3/GSDME axis with the treatment of TNFα+CHX and navitoclax." (PMID 36119049, 2022). "We investigated the relationship between the risk of breast cancer and XRCC3 Thr241Met, XRCC4 G(-1394) T, BAX G(-248) A, and BCL2 C(-938) A gene polymorphisms." (PMID 35320970, 2022). "The BAX expression in breast cancer cell line MCF-7 was upregulated when the apoptosis increasing significantly, caused by the transfection of HCCR-1 siRNA." (PMID 33796128, 2021). "To further test the requirement for canonical MCL-1 function in human breast cancer stem cells we therefore used CRISPR/Cas9 editing to generate MCL1-, BAX/BAK- and MCL1/BAX/BAK-deficient versions of the human breast adenocarcinoma MDA-MB-231 cell line." (PMID 33785871, 2021). "The present case-control study was aimed to examine the association of BCL-2 (-938C> A), BAX (-248G > A), and HER2 (I655V i.e. A > G) polymorphisms with breast cancer risk in Indian population." (PMID 33708254, 2021). "MET treatment also increased the proportion of apoptotic drug‐sensitive and drug‐resistant breast cancer cells, induced cleavage of caspase‐3, increased BAX expression and decreased BCL2 expression." (PMID 32281270, 2020). "Increasing the BAX/BCl2 ratio is an important factor for the induction and processing of apoptosis in breast cancer." (PMID 33369440, 2020). "A significant correlation between the ratios of BAX/ BCL2 was reported to segregate radiosensitive versus radio-resistant breast cancer patients." (PMID 31014274, 2019). "Inhibition of Akt phosphorylation, mTOR and Bcl2 along with increased BAX expression and caspase 3 cleavage are also involved in mediating apoptosis in curcumin treated breast cancer cells." (PMID 31618928, 2019). "In the MCF7 breast cancer cell line there was an increase in BAX, a proapoptotic marker, as the ASX concentration increased up to 25 μM (left)." (PMID 30287735, 2018). "Resveratrol significantly diminished growth of estrogen-positive breast cancer cells inducing apoptosis via reduction of Bcl2/BAX ratio." (PMID 29558948, 2018). "DOX has been reported to induce apoptosis by downregulation of Bcl-XL, an anti-apoptotic molecule, and upregulation of BAX, a pro-apoptotic molecule, in breast cancer cells." (PMID 29559745, 2018). "The increased expression of BAX was validated by real-time qPCR in both LNCaP and breast cancer MCF7 cell lines." (PMID 29381681, 2018).